LGALS3 (galectin 3)
Diseases named in the same sentence as LGALS3 in open-access papers (continued):
Sharing a sentence is not in itself a finding about the gene and the disease.
diabetes (continued). "This concept is consistent with the increased susceptibility of Lgals3−/− mice to IR, inflammation, and diabetes induced by a high-fat diet." (PMID 33208796, 2020). "In pancreatic cancer-associated diabetes, Galectin-3 and S100A9, which are related to DM development were reported to mediate insulin resistance." (PMID 33250773, 2020). "Due to the enormous role of obesity and diabetes as risk factors for endometrial cancer and the fact that galectin 3 is involved in carcinogenesis, we decided to examine its potential as a promising prognostic factor for endometrial cancer." (PMID 32859099, 2020). "We will perform a follow-up exploring the impact of sTWEAK and galectin-3 on cardiovascular complications, comparing with conventional diabetes related risk factors." (PMID 33261587, 2020). "In summary, high ROCK activity and galectin-3 levels were associated with increased risk for AV shunt dysfunction, especially in patients with poorly controlled diabetes." (PMID 31080833, 2019). "High platelet ROCK activity and galectin-3 levels are associated with increased risk in arteriovenous shunt dysfunction, especially in patients with poorly controlled diabetes." (PMID 31080833, 2019). "High platelet ROCK activity and galectin-3 levels are associated with increased risk of arteriovenous shunt dysfunction, especially in patients with poorly controlled diabetes." (PMID 31080833, 2019). "Galectin-3 was also shown to act as a receptor for advanced glycation endproducts, which have been implicated in age-dependent and diabetes-associated bone fragility." (PMID 29160796, 2017). "Moreover, galectin-3 inhibitors have been shown to alleviate diabetes-associated cognitive impairment by reducing oxidative stress and neuroinflammation both in vivo and in vitro, which confirms the important role of galectin-3 in systemic inflammation." (PMID 38755574, 2024). "Interestingly, recent investigations suggest that galectin-3 is involved in cellular metabolism and linked to diabetes and cancer." (PMID 36481721, 2022). "Interestingly, recent studies suggest that galectin-3 is involved in cellular metabolism and linked to diabetes and cancer." (PMID 36481721, 2022). "In summary, LGALS3 rs4644 CC and rs4652 AA genotypes were significantly associated with a higher risk for lower hemoglobin, higher level of parathyroid hormone, and also occurrence of diabetes mellitus and arterial hypertension." (PMID 35807161, 2022). "Therefore, further investigations are needed to establish the exact mechanism by which galectin-3 is involved in the pathogenesis of renal function loss in diabetes." (PMID 36175599, 2022). "Thus, clarifying the potential pathogenic mechanism of Galectin-3 in diabetes and diabetic complications will provide a basis for finding new biomarkers for precision disease prediction and early-diagnosis, and developing potential therapeutic targets." (PMID 35083706, 2022). "The carbohydrate binding protein galectin-3 has been linked to diabetes and cancer." (PMID 36481721, 2022). "In addition, galectin-3 was associated with the need for ICU treatment independently of diabetes (odds ratio: 1.26; 95% confidence interval: 1.07–1.48; p = 0.004)." (PMID 34439802, 2021). "Altogether, these findings point to a possible role of the AGE/RAGE axis in the disorders of bone remodeling associated with aging and diabetes, with galectin-3 as a putative protecting factor through scavenging of AGEs and promotion of osteoblast differentiation and function." (PMID 29160796, 2017). "Compared to healthy controls, persons with T2DM have higher levels of galectin-3 although an earlier study associated low levels with diabetes, suggesting the need for further studies to define the exact role of this glycoprotein in the development of diabetes mellitus." (PMID 40802820, 2025).
diabetes (continued). "By multivariate logistic regression analysis, we found that LGALS3 rs4644 CC and rs4652 AA genotypes were significantly associated with a higher risk for lower hemoglobin, higher level of parathyroid hormone, and also occurrence of diabetes mellitus and arterial hypertension." (PMID 35807161, 2022). "Moreover, other studies supporting a pro-inflammatory role for galectin-3 in the retina showed that loss of galectin-3 is associated with less severe retinal disease and neuroinflammation of the optic nerve tissue during chemically induced diabetes." (PMID 36115971, 2022). "Moreover, binary logistic regression showed that patients who had LGALS3 rs4644 CC and rs4652 AA genotypes had 3.2- and 10-times-higher risk, respectively, of developing diabetes mellitus (p = 0.018; OR = 3.27; CI 1.30–8.60 and p = 0.017; OR = 3.27; CI 1.32–8.13, respectively)." (PMID 35807161, 2022). "Therefore, to optimize the accuracy of assessing diabetes risk, age differences may need to be taken into account with respect to galectin-3 and adiponectin in clinical application." (PMID 34096884, 2021). "In conclusion, high galectin-3 and low adiponectin levels were associated with the risk of type 2 diabetes, and our findings further add evidence that their joint action may be a superior promising parameter for evaluating diabetes risk." (PMID 34096884, 2021). "Galectins, especially galectin-3, are emerging as key players in diabetes complications, promoting fibrosis, inflammation, and vascular damage." (PMID 41750302, 2026). "Together, these data suggest that pharmacological inhibition of Galectin-3 from an early stage is sufficient to ameliorate pancreatic β cell destruction and diabetes in NOD mice." (PMID 41477833, 2026). "At 30 weeks of age, diabetes incidence reached 60.0% in Galectin-3+/+ NOD mice but was significantly reduced to 12.5% in Galectin-3−/− NOD mice (P < 0.01)." (PMID 41477833, 2026). "Pharmacological inhibition (TD139) as well as knockout of Galectin-3 gene both attenuated Galectin-3–mediated suppression of regulatory T cells (Treg cells) and protected from insulitis and diabetes onset in NOD mice." (PMID 41477833, 2026). "The onset of diabetes occurred as early as 13 weeks in Galectin-3+/+ NOD mice, whereas it was delayed to 24 weeks in Galectin-3−/− NOD mice." (PMID 41477833, 2026). "The HFD mice were found to have higher levels of lipocalin-2 (LCN2) and galectin-3 (GAL3), two proteins which play inflammatory roles associated with obesity and diabetes." (PMID 39798403, 2025). "Like galectin-3, sICAM-1 has been studied in both patients with diabetes and those with COVID-19, but findings have varied depending on disease severity, glycemic control, and the presence of complications." (PMID 40733621, 2025). "Considering that the patients with a higher AHI in our study had a higher BMI and had hypertension and diabetes mellitus more often, the potential correlation of galectin-3 with low-grade systemic inflammation should also be taken into account." (PMID 39941305, 2025). "This study evaluated serum galectin-3 and sICAM-1 levels in patients with type 2 diabetes mellitus (T2DM) who were hospitalized with COVID-19 and compared them to those in healthy controls." (PMID 40733621, 2025). "Patients in the high galectin-3 group were older, with the female gender predominating, and had a higher prevalence of diabetes, hypertension, and presentation of AMI." (PMID 40747494, 2025). "Galectin-3 is involved in various conditions such as diabetes, inflammation, fibrosis, rheumatoid arthritis, asthma, certain cancers and heart failure." (PMID 40802820, 2025). "In this study, the association of galectin-3 with other CVD risk factors was adjusted for age, gender, diabetes mellitus and history of cardiovascular event." (PMID 38643287, 2024).
diabetes (continued). "Recently, galectin-3 has been detected in several diseases, such as chronic liver, heart, and kidney diseases, diabetes, viral infection, autoimmune and neurodegenerative diseases, and tumors, and its role as a biomarker has attracted attention." (PMID 38330036, 2024). "Emerging evidence links galectin-3 with systemic proinflammatory-profibrotic responses in conditions such as aortic stenosis and diabetes, suggesting its role in myocardial remodeling and prognosis." (PMID 39063659, 2024). "It must be pointed out that, due to the complexity of the pathogenesis of both diabetes and cancer, the contribution and position of the LPS/galectin-3-Rag GTPases/Ragulator-mTORC1 axis to diabetogenesis and tumorigenesis need more investigations." (PMID 36481721, 2022). "According to existing evidence, Galectin-3 inhibitors such as TD139 can reduce the expression of Galectin-3, thereby improving diabetes and its complications." (PMID 35083706, 2022). "First, our findings showed that ESRD patients with the LGALS3 rs4644 CC and rs4652 AA genotypes and also the CAA haplotype had a higher risk for lower hemoglobin and lower PTH level, and occurrence of diabetes mellitus and arterial hypertension." (PMID 35807161, 2022). "Clinical research has determined that the circulating level of Galectin-3 is closely related to diabetes and its complications, thus it is promising to use Galectin-3 as a predictor and biomarker for those diseases." (PMID 35083706, 2022). "We explore the clinicopathological significance of this axis in cellular glycolysis and in diabetes and cancer and reveal a critical role of galectin-3 in diabetogenesis and tumorigenesis." (PMID 36481721, 2022). "A large number of clinical studies have shown that Galectin-3 is related to the occurrence of diabetes and its complications." (PMID 35083706, 2022). "Increasing evidence has proven that levels of circulating Galectin-3 are elevated in chronic inflammatory diseases including obesity, diabetes and its complications, suggesting that Galectin-3 is closely related to those disease status." (PMID 35083706, 2022). "Serum galectin-3 level was higher in patients with diabetes mellitus and was correlated with values that indicated the left atrial size." (PMID 35039576, 2022). "As a powerful cytokine related to inflammation, autoimmunity, apoptosis, and chemotaxis, Galectin-3 is involved in several metabolic abnormalities, mainly in diabetes and diabetic complications." (PMID 35083706, 2022). "The main conclusion is that the level of serum Galectin-3 is higher in patients with diabetes and its complications." (PMID 35083706, 2022). "This study did shed more light on the potential role of galectin-3/adiponectin in the pathophysiology of diabetes; thus, future studies are warranted to further characterize the link between galectin-3/adiponectin and diabetes." (PMID 34096884, 2021). "On the other hand, galectin-3 is involved in numerous disease mechanisms, which play an important role in cardiac alteration due to diabetes mellitus." (PMID 34561496, 2021). "Therefore, the purpose of our study was to further investigate the relationships among circulating galectin-3 and adiponectin on type 2 diabetes in a community population of different age groups and whether their joint action plays an outstanding role in diabetes risk assessment." (PMID 34096884, 2021). "Use of galectin-3 for assessing cardiac function in prediabetes and type 2 diabetes mellitus (T2DM) needs to be established." (PMID 34561496, 2021). "Patients with type 2 diabetes mellitus had higher serum galectin-3 concentrations than healthy individuals." (PMID 35053194, 2021). "In our study, serum galectin-3 was higher in overweight or obese patients and in those with diabetes." (PMID 34439802, 2021). "Higher serum galectin-3 was observed among patients with hypertension and diabetes, as well as among overweight or obese subjects." (PMID 34439802, 2021).
diabetes (continued). "Adjusted odds ratios for diabetes by quartiles of adiponectin`galectin-3 and galectin-3/adiponectin." (PMID 34096884, 2021). "The diabetes discriminative strength of galectin-3/adiponectin was better in the older population than the younger." (PMID 34096884, 2021). "The combination + lipids + galectin-3/adiponectin model (AUC = 0.72 [95% CIs: 0.66-0.77]) displayed better diabetes assessment performance than the other two models." (PMID 34096884, 2021). "Although two biomarkers show distinct tendencies in obesity and diabetes, growing evidence has revealed that galectin-3 and adiponectin seem to have particular relevance in the pathogenesis of diabetes." (PMID 34096884, 2021). "Aim of the study was to assess galectin-3 as a biomarker for cardiac function in people with euglycaemia, prediabetes and type 2 diabetes mellitus." (PMID 34561496, 2021). "The experimental data links galectin-3 to micro- and macrovascular complications of diabetes and to atherosclerosis." (PMID 34439802, 2021). "ROC curve analysis showed that galectin-3/adiponectin had the best discrimination accuracy for diabetes, especially in Model 3 of group II when compared with adiponectin (area under curve (AUC)=0.712 [95% CI: 0.643–0.780]; P=0.056)." (PMID 34096884, 2021). "Meanwhile, the discriminative strength of the galectin-3/adiponectin ratio for diabetes was better in the older population." (PMID 34096884, 2021). "It was established that inflammatory T-cell mediated autoimmunity in hepatitis, pancreatitis, myocarditis, and type 1 diabetes mellitus, Galectin-3 had strong pro-inflammatory effects." (PMID 32455781, 2020). "We adjusted for age, sex, diabetes duration, galectin-3, metabolic variables, serum-creatinine, smoking, physical inactivity, medication, and cardiovascular complications." (PMID 33261587, 2020). "Galectin-3, inadequate glycemic control and low high-density lipoprotein (HDL)-cholesterol levels were previously linked to depression in these patients with type 1 diabetes mellitus (T1DM)." (PMID 33261587, 2020). "Investigate effects of long-term exercise on the remodeling markers MMP-9, TIMP-1, EMMPRIN and Galectin-3 in combined type 2 diabetes mellitus (T2DM) and coronary artery disease (CAD) patients." (PMID 31890043, 2019). "In patients with poorly controlled diabetes, higher platelet MYPT ratios and galectin-3 levels were more likely than in the patients with well controlled diabetes." (PMID 31080833, 2019). "In this study, in fact, galectin-3 lost its predictive value during multivariate analysis, when considered together with other risk factors such as reduced LVEF, diabetes, and renal impairment." (PMID 30262779, 2018). "There were more women, elderly patients, patients with diabetes mellitus, renal dysfunction, and patients with preexisting chronic (permanent) atrial fibrillation in the group of patients with increased galectin - 3 levels." (PMID 29118378, 2017). "In this view, galectin-3 levels would increase with development of obesity and diabetes, thus serving as a marker of these disorders, in which this lectin exerts a protective effect toward insulin resistance." (PMID 26770660, 2016). "A few studies have investigated the relationship between circulating levels of galectin-3, obesity and parameters of glucose metabolism, and insulin sensitivity in patients with diabetes." (PMID 26770660, 2016). "Previous studies have attributed the protective effects of galectin-3 in diabetes and atherosclerosis to an indirect role in the removal of AGEs from circulation, thereby preventing subsequent tissue damage and activation of the pro-inflammatory RAGE-pathway." (PMID 26047815, 2015). "A recent clinical study has shown that galectin-3 levels correlate with plasma glucose, C-reactive protein, and degree of insulin resistance, suggesting its potential as a biomarker for predicting diabetes and prediabetes." (PMID 26047815, 2015).
diabetes (continued). "Galectin-3 protein expression increases in human atherosclerotic lesions as well as in the aortae of experimental animal models of diabetes." (PMID 26047815, 2015). "Some studies have shown that galectin-3 had independent prognostic value, even after correction for established risk factor such as age, sex, BNP level, renal function, and diabetes mellitus." (PMID 25960597, 2015). "Galectin-3−/− mice were relatively resistant to diabetogenesis as evaluated by glycemia, quantitative histology and insulin content in streptozotocin induced diabetes." (PMID 25302080, 2014). "One report, using an animal model, found that galectin-3+/+mice developed delayed and sustained hyperglycemia in streptozotocin-induced diabetes, mononuclear cellular infiltration and reduced insulin content of islets." (PMID 25302080, 2014). "It is likely that increased Lgals3 expression with diabetes is mediated by increased AGE formation and contributes to inflammatory and vascular components of retinal complications." (PMID 21249158, 2011). "The aim of this study was to explore the serum levels of sICAM-1 and galectin-3 in patients with type 2 diabetes mellitus and COVID-19 and compare them with those in healthy individuals to provide insight into the inflammatory processes associated with this comorbidity." (PMID 40733621, 2025). "It should be emphasised that galectin-3 is not only involved in cancer pathogenesis but also in the pathogenesis of several other diseases such as fibrosis, inflammation and diabetes." (PMID 41023585, 2025). "Furthermore, their findings suggested that galectin-3 plays a significant role in the progression of prediabetes to diabetes." (PMID 40292099, 2025). "Galectin-3 levels have been associated with the progression of CKD in different cohorts, including the general population, patients with CKD, and diabetes, among others." (PMID 40806886, 2025). "Their study indicated that galectin-3 could serve as a marker for the early detection of prediabetes and diabetes." (PMID 40292099, 2025). "Galectin-3, mainly produced and secreted by macrophages, is elevated in diabetes." (PMID 38693121, 2024). "Also, animal models aresuggesting that the elevated levels of galectin-3 foundin the altered metabolic processes such as lipidmetabolism, obesity, diabetes and metabolic syndromemight be acting at the level of pancreatic isletsand adipose tissues." (PMID 39139163, 2024). "Associations between galectin-3, CRP, and PAD were also reportedin patients with diabetes." (PMID 39076571, 2024). "The rare occurrence of diabetes mellitus in ICMP can be explained by an increased level of galectin-3 in the blood, which can interact with the insulin receptor and protein glycation products, promoting their utilization, which prevents the development of insulin resistance." (PMID 37509589, 2023). "Serum level of galectin-3 is significantly higher in PCOS subjects, is associated with insulin resistance and has been proposed as a biomarker for detecting prediabetes, diabetes and inflammation." (PMID 37033997, 2023). "Moreover, the current study is limited by the availability of the diabetes and cancer data with respect to the LPS/galectin-3-Rag GTPases/Ragulator-mTORC1 axis." (PMID 36481721, 2022). "This study aimed to investigate the association between galectin-3 concentration and estimated glomerular filtration rate (eGFR) in patients with type 2 diabetes mellitus (T2DM) with and without albuminuria." (PMID 36175599, 2022). "This is consistent with not only our proposition that galectin-3 is a sensor of LPS, but also our observations that LPS/galectin-3 is involved in the development of diabetes and cancer, both pathological states are intimately associated with inflammatory responses." (PMID 36481721, 2022). "The findings of this study suggested that Galectin-3 may play a role in the progression of prediabetes stage to diabetes stage." (PMID 35083706, 2022).